CRP (C-reactive protein)
Diseases named in the same sentence as CRP in open-access papers (continued):
Sharing a sentence is not in itself a finding about the gene and the disease.
malnutrition (continued). "Moreover, CRP is a good predictor of malnutrition and the overall and cardiovascular disease mortality rates in CKD patients." (PMID 38386646, 2024). "However, the report of Heimbürger showed that high serum CRP is an independent determinant of malnutrition in CKD, contrary to our study." (PMID 39118666, 2024). "Conclusively, our data suggest a prominent link between CRP and malnutrition, however, incorporation of assessment tools such as the GNRI score may alter this relationship, specifically in older patients." (PMID 38850122, 2024). "Therefore, CRP is probably less sensitive as a criterion for malnutrition in the chronic phase of SCI." (PMID 38571922, 2024). "However, elevated NT-proBNP can result not only from cardiac causes but also from impaired renal function, atrial fibrillation, older age, malnutrition (low albumin), or high levels of C-reactive-protein." (PMID 38191350, 2024). "Given the limitations of inflammatory markers like CRP in distinguishing between inflammation and malnutrition, alternative approaches such as the combined use of inflammatory and non-inflammatory biomarkers or the development of more specific markers like certain cytokine profiles are suggested." (PMID 39125381, 2024). "Patients with an eGFRcys-to-eGFRcre ratio <0.7 had lower median mGFR, higher rates of malnutrition and smoking, and higher levels of acute and chronic inflammation as reflected by median C-reactive protein and soluble urokinase plasminogen activator receptor, respectively." (PMID 39081739, 2024). "Clinical variables such as body mass index, comorbidities, malnutrition inflammation, quality of life, fasting glycemia, glycosylated hemoglobin, hematocrit, uremia, creatinine, sodium, calcium, potassium, albumin, ferritin, C reactive protein were measured." (PMID 39723266, 2024). "This study also confirmed malnutrition in patients with high CRP." (PMID 39070256, 2024). "Despite the significant link between CRP and malnutrition, their relationship may be influenced in older groups considering the sensitivity of GNRI due to ageing factors." (PMID 38850122, 2024). "Additionally, elevated CWT demonstrated a propensity to align with higher levels of C-reactive protein and indications of malnutrition." (PMID 38137728, 2023). "The present study observed a significant correlation between CRP levels and malnutrition." (PMID 37521420, 2023). "Furthermore, the inflammation marker CRP was higher than the normal values, suggesting a tendency toward malnutrition and inflammation." (PMID 36983118, 2023). "In light of these findings, high CRP levels and low lymphocyte counts may represent a poor immune response in the host, increased systemic inflammatory conditions, and malnutrition." (PMID 37438696, 2023). "While activation of inflammation pathways especially characterizes cachexia, we did not observe a significant association of C-reactive protein with malnutrition." (PMID 36975418, 2023). "Regular CRP assessment can improve malnutrition management in patients with peritoneal dialysis." (PMID 37304869, 2023). "A receiver operating characteristic (ROC) curve was plotted to determine the cut-off values of different specific indicators of malnutrition (adults: BMI and CRP; adolescents: Z-score) for predicting the occurrence of LP and to evaluate their predictive efficacy." (PMID 35967822, 2022). "Previous studies have reported that C-reactive protein (CRP), MSKCC model, modified Glasgow Prognostic Score (mGPS), and malnutrition are significantly associated with prognostic factors for progression-free survival (PFS) and overall survival (OS) of mRCC treated with sunitinib." (PMID 36434552, 2022). "Compared to the patients in Quartile 1, patients in the highest quartile (Quartile 4) who consumed a more pro-inflammatory diet may have lower muscle mass and strength, as well as higher CRP scores and a higher prevalence of sarcopenia and malnutrition." (PMID 35215553, 2022).
malnutrition (continued). "Therefore, CRP, and thus immune activation, correlates reciprocally with serum albumin levels, which is generally considered a marker of malnutrition and liver function." (PMID 35327399, 2022). "In the case of both parameters, there was a statically significant difference between no malnourished patients and those with severe malnutrition (serum albumin p < 0.001, CRP p < 0.05) and between those with moderate and severe malnutrition (serum albumin p = 0.0013, CRP p = 0.0013)." (PMID 35276861, 2022). "Additionally, HbA1c was also positively correlated with hemoglobin (β = 0.023; p = 0.019) and log CRP (β = 0.040; p = 0.038) and negatively correlated with malnutrition–inflammation (β = −0.056; p = 0.043)." (PMID 36009406, 2022). "CRP levels in patients not at risk with a diagnosis of malnutrition were also lower than in patients at risk with a diagnosis of malnutrition, suggesting that inflammation measured by CRP also was relevant for the diagnosis." (PMID 36396666, 2022). "The CRP/ALB ratio, a combined index of the ALB and CRP levels, is known to be related more consistently to prognosis than a single marker, accurately reflecting the degree of inflammation or nutritional deficiency." (PMID 36704518, 2022). "Our findings suggest that the mGPS, which is a combination of serum CRP and albumin levels, might serve as an indicator of chronic inflammation and malnutrition, which result in a worse prognosis." (PMID 33866376, 2021). "Hepcidin was the main determinant of an SFH <10th centile (CLAP) and an SFH <3rd centile (INTERGROWTH), and hepcidin was associated with indicators of inflammation (ferritin, IL-17, CRP) and indirect indicators of hypovolemia and malnutrition (lower urinary pH and higher intake of MNS)." (PMID 33898918, 2021). "Nevertheless, CRP may indicate whether serum protein concentrations of albumin are reduced because of inflammatory processes or malnutrition." (PMID 34072686, 2021). "The MNA-SF and NRS-2002 tools showed that malnutrition risk was not significantly correlated with age, gender, serum albumin, but was correlated with lower phase angle, CRP, and muscle strength in elderly patients." (PMID 31388102, 2020). "The strong relationship between malnutrition and inflammation in dialysis patients is evident, as indicated by significant association (r = 0.65, p = 0.040) of malnourished HD patients categorized by SGA B and C with high C-reactive protein (CRP) levels." (PMID 33076282, 2020). "We acknowledge that some studies investigating Hb, Alb and CRP outside of a focus on malnutrition may have been missed for this population." (PMID 32366995, 2020). "In a stepwise multiple regression analysis, the effects of mobility (parker mobility score), FFM, TSH, inflammation (CRP) and malnutrition (MNA-LF score) (as independent variables) on the difference between REEmeasured and REEpredicted (as dependent variable) on admission were tested." (PMID 32727100, 2020). "In CKD we assessed serum C-reactive protein, blood neutrophil/lymphocyte ratio, Malnutrition-inflammation Score (MIS); gMB was studied by denaturing gel gradient electrophoresis (DGGE), high-throughput sequencing (16S r-RNA gene), and quantitative real-time PCR (RT-PCR)." (PMID 32236095, 2020). "The multivariate regression model with ICW as the dependent variable showed that male sex, MUAMC, and LTM were independently associated with higher ICW and inflammation, assessed as CRP; with lower ICW after adjustment for age, nPCR, plasma creatinine, and the presence of malnutrition (PEW)." (PMID 33182670, 2020). "The observed associations between seasonal variation in vitamin D and CRP, PRE, and the indices of malnutrition and inflammation (PINI, CSI, CRP/PRE) were significant only in a subgroup of patients, thus being too small to allow for multiple statistical analyses adjusted for confounders." (PMID 32188088, 2020).
malnutrition (continued). "However, the prognostic value of CRP and albumin in patients with reduced liver synthesis (e.g., malnutrition, liver cirrhosis, cancer, advanced age, or chronic heart failure) is limited." (PMID 32344777, 2020). "In addition, regardless of the used criterion for the detection and classification of malnutrition, albumin and prealbumin values were significantly lower and CRP higher than in normally nourished patients, consequently altering the Glasgow prognostic score." (PMID 31480635, 2019). "Biomarkers for malnutrition and inflammation are low serum albumin and elevated hs-CRP." (PMID 31480661, 2019). "Based on the biochemical profile at admission serum sodium, potassium, albumin, CRP levels and haemoglobin were lower in patients at malnutrition risk compared to patients with no risk for malnutrition (p<0.2)." (PMID 30677081, 2019). "The CRP/ALB ratio, a combined index of the ALB and CRP levels, is known to be related more consistently to prognosis than is CRP or ALB alone, and it may accurately reflect the degree of inflammation or nutritional deficiency." (PMID 31821367, 2019). "In addition, the Glasgow prognostic score (GPS) based on serum CRP (an acute-phase response protein) and albumin levels (a typical index of malnutrition) was developed to aid in appreciating the role of leukocytosis." (PMID 30369930, 2018). "The lipid profile of the patients suggests the presence of malnutrition as 50% had low levels of cholesterol those who did not survive had lower serum triglycerides, urea, creatinine, P and iron levels and high serum levels of CRP, all of which are indirect effects of malnutrition." (PMID 28045952, 2017). "Il a été noté une élévation de la CRP dans les deux formes de malnutrition." (PMID 26161222, 2015). "In our study, the significant interaction suggests that the effect of malnutrition on the outcome (low plasma selenium) depends on CRP concentration and the effect of CRP on the outcome depends on whether the child is malnourished or not." (PMID 24886623, 2014). "• The effect of malnutrition on low plasma selenium depends on CRP concentrations." (PMID 24886623, 2014). "CRP, a systemic inflammatory marker, increased in the malnutrition hemodialysis patients." (PMID 24349471, 2013). "While C-reactive protein (CRP)-to-prealbumin and CRP-to-albumin ratios may enhance the predictive value of individual biomarkers for mortality and severe disease-related malnutrition, their limited standalone accuracy underscores the need for further studies and combined clinical interpretation." (PMID 41036189, 2025). "Moreover, there is growing interest in the potential utility of integrating the CONUT score with markers of systemic inflammation, such as C-reactive protein (CRP) and interleukin-6, to more accurately capture the complex relationship between malnutrition, immune activation, and cardiac dysfunction." (PMID 40431475, 2025). "In the multivariable beta regression model, malnutrition remained a significant and independent predictor of a higher proportion of time spent in relative intraoperative hypotension (P < 0.001), even after adjusting for age, sex, albumin, CRP, and other relevant covariates." (PMID 41257946, 2025). "Therefore, we believe CRP should be interpreted with caution, and contemporary nutritional indices—such as the CRP-to-albumin ratio (CAR) or the CRP-to-prealbumin ratio (CPR)—should be incorporated into the assessment of malnutrition in critically ill patients." (PMID 41515189, 2025). "Additionally, our findings suggest that age may act as a mediator between CRP and malnutrition assessed via GNRI, implying that GNRI, originally designed for older patients, may be more responsive to higher inflammation levels associated with ageing." (PMID 38850122, 2024).
malnutrition (continued). "Moreover, CRP levels were considerably higher, and vitamin D levels were significantly lower in chronic psychotic patients compared to newly diagnosed psychosis, which can highlight the major effects of chronic inflammatory processes and malnutrition." (PMID 37803327, 2023). "Clinical studies have established that cachexia is not a nutritional deficiency and is linked to expression of certain proteins (e.g., interleukin-6 and C-reactive protein), but much remains unknown about this often fatal syndrome." (PMID 36973755, 2023). "Although no attention was given to C-reactive protein measurements in the present study, the number of patients with a weight loss of ˃ 5% may indicate that about half of the population was at risk for malnutrition." (PMID 35426524, 2022). "First, we used CRP as an objective measure for inflammation instead of the presence of metastatic disease, the latter of which may have resulted in some under–reporting of malnutrition in the Steer study." (PMID 36483923, 2022). "In addition, the Global Leadership Initiative on Malnutrition (GLIM) guidelines suggest that serum CRP could be used as a surrogate to evaluate the presence and severity of disease/inflammation, which contribute to the development of malnutrition." (PMID 35619955, 2022). "Furthermore, it has been demonstrated in older patients with hematological malignancies that individuals with malnutrition had more often inflammation (as measured by elevated CRP and low albumin) and suffered from impairments in mood, performance status, and fatigue." (PMID 34476573, 2021). "However, as the pathological mechanisms of ESLD (i.e., hepatic insufficiency and/or malnutrition) may negatively influence CRP and ALB production, cirrhotic patients have always been excluded from previous studies." (PMID 31821367, 2019). "SBS as a model of extreme malnutrition was associated with substantially elevated levels of both ANGPTL3 and 4, which might at least partially be attributed to their initially increased proinflammatory status as evidenced by markedly high CRP levels." (PMID 29695708, 2018). "Therefore, in our underweight elderly patients, high levels of IL-6 and CRP might result from a cumulative action of immunoaging and undernutrition/malnutrition." (PMID 27274758, 2016). "Moreover, correlation between CRP level and body composition indicated that inflammation may be a powerful predictor of malnutrition in CRE patients." (PMID 27233356, 2016). "Combined estimations of weight loss, serum measurements of CRP,albumin, urea, creatinine and alkaline phosphatase, preferably combined with othermethods using scores such as ECOG-PS, GPS and PG-SGA, were associated with relevantclinical outcomes such as malnutrition, survival and mortality." (PMID 26270855, 2015). "However, some studies indicated that albumin, as a marker of malnutrition, and not CRP, was associated with mortality in dialysis patients." (PMID 23300770, 2012). "This prospective, multicenter cohort study (AFEDIN - Analysis of the Etiological Factors of Malnutrition: Inflammation and Intake) included 266 ambulatory patients with DRM and CRP > 3 mg/L." (PMID 42253739, 2026). "For example, C-reactive protein (CRP), erythrocyte sedimentation rate (ESR), and albumin lack sensitivity, and systemic inflammation or malnutrition can influence these biomarkers." (PMID 40305512, 2025). "Our nomogram identifies high-risk patients by integrating variables such as hyperglycemia, malnutrition (low PA), cardiac dysfunction (elevated BNP), and systemic inflammation (elevated CRP/WBC)." (PMID 40529443, 2025). "Future investigations should establish longitudinal monitoring frameworks integrating CRP, IL-6, and TNF-α to disrupt the “inflammation-malnutrition” vicious cycle and improve long-term outcomes." (PMID 40630494, 2025).
malnutrition (continued). "CRP levels may be a valuable component in evaluating the nutritional status of cardiovascular patients, as it can help differentiate between acute and chronic inflammatory conditions, supporting the accurate classification of malnutrition according to the GLIM criteria." (PMID 40871731, 2025). "Patients with malnutrition showed lower levels of WBC, neutrophils, lymphocytes, total cholesterol, and LDL cholesterol, as well as higher levels of HbA1c, CRP, and the TyG index." (PMID 41463388, 2025). "It is particularly relevant to include inflammatory and functional biomarkers (such as CRP, IL-6, MIS, or PINI) as secondary endpoints to better characterise the malnutrition–inflammation complex and its response to therapy." (PMID 41228549, 2025). "Inflammatory markers such as CRP and TNF-α can suppress appetite, impairing protein and fat metabolism, which ultimately leads to malnutrition." (PMID 40655484, 2025). "The four tools, the PNI, GNRI, GLIM and mGPS, add immune indices as indicators of malnutrition; the PNI and GNRI use lymphocyte counts, and the GLIM and mGPS use C-reactive protein (CRP)." (PMID 41141259, 2025). "In the context of the biochemical milieu, frail patients exhibited lower serum albumin and GFR levels, alongside higher C-reactive protein (CRP) levels, indicating a state of chronic inflammation and malnutrition." (PMID 40283583, 2025). "Group B, which received the combined therapy, showed better results compared to group A, with reduced malnutrition grades and lower levels of inflammatory markers such as TNF-α, CRP, and IL-6 after treatment." (PMID 41281287, 2025). "Based on the PNI value, which evaluates both inflammatory and nutritional statuses through ALB and CRP levels, it was established that 65% of T2DM patients demonstrated mild malnutrition." (PMID 40284203, 2025). "In the subsequent beta regression analysis, malnutrition remained a significant and independent predictor of increased relative IOH proportion after adjusting for age, sex, albumin, CRP, surgical approach, baseline MAP, and intraoperative factors." (PMID 41257946, 2025). "Primary outcomes were albumin (Nutritional marker used to assess malnutrition), CRP(C-reactive protein biomarker for systemic inflammation), IgA, interleukins, weight, quality of life, complications, and mortality." (PMID 41235306, 2025). "In summary, elevated CRP levels and WBC counts reflect an inflammatory response that can promote tumor growth and metastasis, while low albumin levels indicate malnutrition and chronic inflammation." (PMID 39513125, 2024). "Inflammatory markers such as C-reactive protein (CRP), interleukins (e.g., IL-6), and tumor necrosis factor-alpha (TNF-α) are commonly used to assess malnutrition in the elderly." (PMID 39125381, 2024). "The risk factors of sarcopenia were known to be age, a longer disease duration, malnutrition, DAS28, C-reactive protein, menopause, and rheumatoid factor seropositivity." (PMID 38541081, 2024). "GLIM, created by four societies, is the first international malnutrition standard including inflammation, and it provides a more comprehensive assessment than the GPS, which uses only albumin and CRP." (PMID 39734937, 2024). "The high heterogeneity observed for the differences in BNP and CRP following the assessment of GNRI and CONUT scores for those with (mild) malnutrition versus normal nutrition was further explored by employing multiple meta‐regression analyses." (PMID 38850122, 2024). "Based on the GPS value, which reflects both the inflammatory and nutritional status using ALB and CRP levels, we found that 39% of T2DM patients had moderate-to-severe malnutrition status." (PMID 39682569, 2024). "Specifically, ESR, CRP, NLR, MPV, and ferritin levels were higher in patients with malnutrition compared to other groups, also showing a significant positive correlation." (PMID 38474705, 2024).